LARGE1 (LARGE xylosyl- and glucuronyltransferase 1)
Description:
Bifunctional glycosyltransferase with both alpha-1,3-xylosyltransferase and beta-1,3-glucuronyltransferase activities involved in the maturation of alpha-dystroglycan (DAG1) by glycosylation leading to DAG1 binding to laminin G-like domain-containing extracellular proteins with high affinity. Elongates the glucuronyl-beta-1,4-xylose-beta disaccharide primer structure initiated by B4GAT1 by adding repeating units [-3-Xylose-alpha-1,3-GlcA-beta-1-] to produce a heteropolysaccharide. Requires the phosphorylation of core M3 (O-mannosyl trisaccharide) by POMK to elongate the glucuronyl-beta-1,4-xylose-beta disaccharide primer. Plays a key role in skeletal muscle function and regeneration (By similarity).
Synonyms: KIAA0609; LARGE; MDC1D; MDDGA6; MDDGB6
Tractability: Small molecule: a structure with a bound ligand is known. Antibody: UniProt predicts a signal peptide or a membrane-spanning region; its Gene Ontology location is reachable by antibodies, with medium confidence.
Target class: Enzyme; Transferase
Gene: Protein-coding gene on chromosome 22 (33,162,226 to 33,922,885, reverse strand). Ensembl gene ENSG00000133424.
Subcellular location: Golgi apparatus membrane
Pathways (Reactome):
Disease: Defective LARGE causes MDDGA6 and MDDGB6
Metabolism of proteins: Matriglycan biosynthesis on DAG1
Gene Ontology:
Molecular function: glucuronosyltransferase activity; hexosyltransferase activity; manganese ion binding; xylosyltransferase activity; acetylglucosaminyltransferase activity; glycosyltransferase activity; UDP-xylosyltransferase activity
Biological process: glycoprotein biosynthetic process; protein O-linked glycosylation via mannose; glycosphingolipid biosynthetic process; muscle cell cellular homeostasis; N-acetylglucosamine metabolic process; negative regulation of muscle cell apoptotic process; positive regulation of phosphatidylinositol 3-kinase/protein kinase B signal transduction; positive regulation of Rac protein signal transduction; positive regulation of skeletal muscle acetylcholine-gated channel clustering; protein O-linked glycosylation; skeletal muscle organ development; skeletal muscle tissue regeneration
Cellular component: Golgi apparatus; Golgi membrane; neuromuscular junction; plasma membrane
Genetic constraint (gnomAD): Loss-of-function variants: 42 observed, 89.69 expected, observed/expected ratio (o/e) 0.47, 90% interval 0.37 to 0.61. The upper end of that interval is the gene's LOEUF score, 0.61, which puts it in group 2 of 6, group 1 being the genes least tolerant of losing a copy. Missense variants: 800 observed, 1,039.5 expected, observed/expected ratio (o/e) 0.77, 90% interval 0.73 to 0.82. Synonymous variants: 434 observed, 415.32 expected, observed/expected ratio (o/e) 1.04, 90% interval 0.96 to 1.13.
Gene-disease validity (ClinGen):
ClinGen rates the evidence that LARGE1 causes each of these diseases.
muscular dystrophy-dystroglycanopathy (autosomal recessive): Definitive.
Homologues: Orthologues: chimpanzee LARGE1 (100% identical), macaque LARGE1 (99% identical), rabbit LARGE1 (99% identical), mouse Large1 (98% identical), pig LARGE1 (97% identical), rat Large1 (97% identical), dog LARGE1 (97% identical), guinea pig LARGE1 (96% identical), tropical clawed frog large1 (93% identical), zebrafish large1 (85% identical), Caenorhabditis elegans lge-1 (29% identical), Drosophila melanogaster CG11149 (12% identical), and 10 more. Paralogues in human: LARGE2 (62% identical), B4GAT1 (14% identical), GXYLT1 (12% identical), GXYLT2 (11% identical), XXYLT1 (10% identical).
Diseases named in the same sentence as LARGE1 in open-access papers:
LARGE1 is named in the same sentence as 56 diseases in open-access papers, as found by Europe PMC text mining. Sharing a sentence is not in itself a finding about the gene and the disease. The quoted sentences say what the papers report.
dystroglycanopathies (20 papers, 2010 to 2024). "Mutations specifically within the LARGE1 gene can cause severe forms of secondary dystroglycanopathies." (PMID 36512577, 2022). "Mutations in the LARGE1 gene have been shown to cause life-threatening dystroglycanopathies through the inhibition of matriglycan synthesis." (PMID 36512577, 2022). "Due to the enrichment of regulatory variants in FKTN and DTNA, we expanded our search to additional dystroglycanopathy genes (LARGE1, POMT1, POMT2) and identified two regulatory variants of interest in LARGE1 in gene-elusive cases." (PMID 35288587, 2022). "Both are among the most severe of the dystroglycanopathies and are caused by recessive mutations in LARGE1, encoding the LARGE xylosyl- and glucuronyltransferase 1 protein." (PMID 34142127, 2021). "Other genes contributing to dystroglycanopathies through glycosylation errors include POMT1, POMT2, POMGNT1, FKRP, ISPD and LARGE1." (PMID 38439105, 2024).
muscular dystrophy (13 papers, 2009 to 2023). Muscular dystrophy (MD) refers to a group of more than 30 genetic diseases characterized by progressive weakness and degeneration of the skeletal muscles that control movement. "Collectively, our study demonstrates that phosphorylation of core M3 by POMK enables LARGE1 to elongate matriglycan on α-DG, thereby preventing muscular dystrophy." (PMID 32975514, 2020). "Although germline mutations in LARGE1 have been reported in a group of congenital muscular dystrophies that also involve brain and eye defects, no increase in the rate of any cancer type, including RMS, has been described in patients." (PMID 31054580, 2019).
congenital muscular dystrophy (6 papers, 2017 to 2025). A muscular dystrophy that is characterized by diminished muscle tone (hypotonia), progressive muscle weakness and degeneration (atrophy), abnormally fixed joints, spinal rigidity, and delays in reaching motor milestones such as sitting or standing unassisted. "MYOCD is associated with muscular atrophy, whereas LARGE1 is related to congenital muscular dystrophy." (PMID 40600194, 2025). "It has also been reported that mutations in the Large1 gene induce abnormal glycosylation of α-dystroglycan and result in congenital muscular dystrophy." (PMID 36568890, 2022). "The spectrum of muscular dystrophies in dogs has also expanded in recent years to include forms of limb–girdle muscular dystrophy associated with variants in sarcoglycan genes (SGCD and SGCA) and congenital muscular dystrophies with variants identified in the COL6, LAMA2, and LARGE1 genes." (PMID 37628610, 2023).
Lassa fever (3 papers, 2012 to 2024). A viral hemorrhagic fever that is caused by the Lassa virus, which is transmitted by contact with infected rodents; it is characterized by fever, headache, malaise, myalgia, and hearing loss. "Larger cohorts and deeper phenotypic characterization will be required to evaluate the hypothesis of LARGE1 mediated genetic resistance to Lassa fever susceptibility." (PMID 38326571, 2024). "Therefore, a variant in the putative region under positive selection may have been driven to high allele frequencies by impacting expression levels of LARGE1, thereby reducing the risk of severe Lassa fever." (PMID 38326571, 2024). "GWAS in difficult-to-recruit populations identifies variants associated with Lassa fever outcome and susceptibility at loci proximal to LIF, GRM7 and LARGE1." (PMID 38326571, 2024). "We also show that a haplotype bearing signatures of positive selection and overlapping LARGE1, a required LASV entry factor, is associated with decreased risk of Lassa fever in the Nigerian cohort but not in the Sierra Leone cohort." (PMID 38326571, 2024).
autism (2 papers, 2009 to 2022). Persistent deficits in social interaction and communication and interaction as well as a markedly restricted repertoire of activity and interest as well as repetitive patterns of behavior. "Three genes that encode anabolic enzymes, which are among the 107 DEGGs, have been reported as candidate genes for autism, and they are Large1, Galnt9, and Hs3st5." (PMID 36568890, 2022). "Our expression profiles analysis showed that the Large1 gene was down-regulated in VPA rats, indicating that VPA-induced autism is closely related to the abnormal expression of autism candidate genes." (PMID 36568890, 2022).
breast carcinoma (2 papers, 2015 to 2022). "This could be attributed to the downregulation of B4GAT1 and LARGE1 genes existing in prostate cancer cell lines, as it was also the case for breast cancer cell lines." (PMID 36494657, 2022). "In a coherent fashion, LARGE1 mRNA levels were very low or undetectable in the PC3 prostate cancer line and in a variety (a total of ten) of breast cancer cell lines examined, including MDA-MB-231." (PMID 36494657, 2022). "Also consistently, its LARGE1 protein product was virtually absent in the MDA-MB-231 breast cancer cell line and in the three glioblastoma cell lines just cited above." (PMID 36494657, 2022).
epilepsy (2 papers, 2024 to 2025). A brain disorder characterized by episodes of abnormally increased neuronal discharge resulting in transient episodes of sensory or motor neurological dysfunction, or psychic dysfunction. "Although the direct effects of CLCNKB and LARGE1 in epilepsy require further validation, their roles in ion channel function and the glycosylation modification offer new perspectives for research." (PMID 40600194, 2025). "In our study, CLCNKB was identified through genetic screening in an epilepsy-affected family, whereas LARGE1 emerged from subsequent sequencing data analysis." (PMID 40600194, 2025). "We focused particularly on the roles of the CLCNKB and LARGE1 genes, which are involved in regulating neuronal excitability and the glycosylation modifications, potentially implicating them in the pathogenesis of epilepsy." (PMID 40600194, 2025). "Specifically, LARGE1 plays a crucial role in modifying the glycan structures on the surface of neural cells, and these alterations may affect synaptic plasticity and signal transmission between neurons, thereby promoting the development of epilepsy." (PMID 40600194, 2025).
rhabdomyosarcoma (2 papers, 2019 to 2022). A rare aggressive malignant mesenchymal neoplasm arising from skeletal muscle. "In human rhabdomyosarcoma biopsies and a number of epithelial cancer-derived cell lines, an anomalous silencing of the LARGE1 gene has been determined to be a primary cause of loss of laminin binding by DG." (PMID 36494657, 2022). "The current study is focused on establishing a proof of principle that LARGE1-driven loss of matriglycan is a common feature in rhabdomyosarcomas." (PMID 31054580, 2019).
COVID-19 (1 paper, 2023). A disease caused by infection with severe acute respiratory syndrome coronavirus 2. "Given that this disease affects cardiac function and even leads to heart failure, the altered expression of LARGE1 in cardiac myocytes caused by COVID-19 may have an adverse effect on the heart." (PMID 37109540, 2023). "Although no direct evidence has shown that LARGE1 gene expression is altered in patients with COVID-19, two studies on the Lassa fever virus, which also contains spike proteins, found LARGE1 gene overexpression." (PMID 37109540, 2023).
diabetes (1 paper, 2018). "No previous studies have indicated a link between LARGE1 and type 2 diabetes in additive model GWAS, nor did we replicate our findings in recessive analysis in a Danish sample of 5220 individuals with diabetes and 18,556 control participants." (PMID 29926116, 2018).
glioblastoma (1 paper, 2022). The most malignant astrocytic tumor (WHO grade IV). "Consequently, a loss of somatic copies of the LARGE1 gene has been reported in patients with primary glioblastoma, this being related to an increase of Ki-67+ cells and a shortened survival." (PMID 36494657, 2022).
hepatic cancer (1 paper, 2022). "On the other hand, a significant overexpression of LARGE1 mRNA was observed in squamous cell carcinoma of head and neck and hepatic cancer (by ~ 5-fold), being associated in the latter with a low patient survival." (PMID 36494657, 2022). "However, overexpression of the LARGE1 mRNA has been detected in the hepatic cancer cell lines Huh7 (by 6.20-fold), Hep G2 (by 4.40-fold) and SMMC-7721 (by 7.50-fold), in correlation with cell growth, proliferation, migration, invasiveness and cell cycle." (PMID 36494657, 2022).
Kyphoscoliosis (1 paper, 2021). An abnormal curvature of the spine in both a coronal (lateral) and sagittal (back-to-front) plane. "Mice lacking Large1, as in the spontaneous myd mouse line, show reduced survival, reduced growth and kyphoscoliosis." (PMID 34142127, 2021).
leukemia (1 paper, 2022). A malignant (clonal) hematologic disorder, involving hematopoietic stem cells and characterized by the presence of primitive or atypical myeloid or lymphoid cells in the bone marrow and the blood. "Furthemore, in solid tumors and derived cell lines (i.e., leaving aside leukemia) genes directly involved in the synthesis of core M3 glycan and matriglycan, such as POMGNT2, CRPPA, B4GAT1, LARGE1 and LARGE2 and/or their encoded proteins, are found downregulated." (PMID 36494657, 2022).
leukodystrophy (1 paper, 2021). Leukodystrophies are a group of rare, progressive, metabolic, genetic diseases that affect the brain, spinal cord and often the peripheral nerves. "As proof of concept, we present novel mouse models for multiple known human diseases representing different developmental etiologies, including segmentation defects (Hes7), leukodystrophy (Galc) and neuromuscular disease (Clcn1 and Large1)." (PMID 34142127, 2021).
microcephaly (1 paper, 2025). A congenital or acquired developmental disorder in which the circumference of the head is smaller than normal for the person's age and sex. "In cones, several genes associated with cell migration (LARGE1), mechanistic target of rapamycin (mTOR) signaling (RICTOR), microcephaly (XRCC4), and intellectual developmental disorder (FMN2) were strongly dysregulated." (PMID 40706588, 2025).
muscular dystrophy-dystroglycanopathy (1 paper, 2024). "Recessive pathogenic variants in LARGE1 lead to muscular dystrophy-dystroglycanopathy (congenital with brain and eye anomalies type A6; MIM: 613,154) and muscular dystrophy-dystroglycanopathy (congenital with mental retardation type B6; MIM: 608,840)." (PMID 38470509, 2024).
type 2 diabetes (1 paper, 2018). "In this study, we observed three loci, TBC1D4, ITGA1 and LARGE1, harbouring variants with large recessive effects on the risk of type 2 diabetes in Greenlanders, the latter, however, having weaker statistical support." (PMID 29926116, 2018). "The novel variants in ITGA1 and LARGE1 had a high impact on risk of type 2 diabetes in Greenlanders, evident by the estimated effect sizes and by the higher frequency of type 2 diabetes among homozygous carriers compared with non-carriers (24.9% and 28.9% vs 10%)." (PMID 29926116, 2018). "Using a recessive genetic model, we identified two novel loci associated with type 2 diabetes in Greenlanders, namely rs870992 in ITGA1 on chromosome 5 (OR 2.79, p = 1.8 × 10−8), and rs16993330 upstream of LARGE1 on chromosome 22 (OR 3.52, p = 1.3 × 10−7)." (PMID 29926116, 2018). "Besides the established TBC1D4 locus, we identified a novel genome-wide significant variant for risk of type 2 diabetes in ITGA1, and a variant near LARGE1 showing a suggestive association." (PMID 29926116, 2018).
cancer (12 papers, 2011 to 2022). A tumor composed of atypical neoplastic, often pleomorphic cells that invade other tissues. "After the metastatic cancer cell has reached its secondary site, it may restore LARGE1 expression in order to orchestrate the remodeling of the ECM in the growing secondary tumor." (PMID 31054580, 2019). "Interestingly, the LARGE1 gene was originally identified at a chromosomal region frequently deleted in human meningiomas that, since it falls within a common fragile site, it is prone to suffer breaks and deletions in other cancer types." (PMID 36494657, 2022). "However, it should be noted that an absent expression of LARGE1 protein has been found in tongue squamous cell carcinoma, which statistically correlated with a reduction in glycosylated α-DG levels in this pathologic type of cancer." (PMID 36494657, 2022).
neuromuscular disease (2 papers, 2021 to 2024). "This decision was also motivated by the known role of LARGE1 in the genesis of neuromuscular diseases (MIM: 608,840 & MIM:613,154)." (PMID 38470509, 2024). "LARGE1 was also significantly decreased in serum samples derived from disease controls reflecting other neuromuscular diseases with impaired neuromuscular transmission compared to the level detected in SMA-patients." (PMID 38470509, 2024).
neurological diseases (1 paper, 2024). "The observed decrease of LARGE1 in CSF and serum derived from patients suffering from other neurological diseases support the concept of a protective role of LARGE1 in SMA." (PMID 38470509, 2024). "Functional studies ideally on mouse models representing the different onset forms of SMA are crucial to address the exact role of LARGE1 increase in different tissues in relation to varying severity grades of this neurological disorder." (PMID 38470509, 2024).
LARGE1 also shares sentences with these, for which no sentence is quoted: tumor (7 papers); Walker-Warburg syndrome (6); Alzheimer disease (2); Duchenne muscular dystrophy (2); muscle-eye-brain disease (2); prostate carcinoma (2); schizophrenia (2); Becker muscular dystrophy (1); bipolar disorder (1); calpainopathy (1); Cerebellar hypoplasia (1); cobblestone lissencephaly (1); Cognitive impairment (1); congenital muscular dystrophy type 1D (1); congenital myopathies (1); depression (1); dysferlinopathy (1); dystrophinopathy (1); Fukuyama congenital muscular dystrophy (1); genetic diseases (1); heart failure (1); Hydrocephalus (1); Insulin resistance (1); Intellectual disability (1); limb-girdle muscular dystrophy (1); Lissencephaly (1); motor neuron diseases (1); muscular atrophy (1); neuroblastoma (1); Neuronal Migration Disorder (1).
A further 5 diseases each share a sentence with LARGE1 in 1 paper.